DISC1 (DISC1 scaffold protein)
Diseases named in the same sentence as DISC1 in open-access papers (continued):
Sharing a sentence is not in itself a finding about the gene and the disease.
schizophrenia (continued). "Thus, we hypothesized that the common DISC1 gene variant R264Q DISC1, located within the binding region with the D2R could alter the strength of the DISC1-D2R interaction and have functional consequences related to the pathophysiology of schizophrenia." (PMID 32493513, 2020). "Disruption in schizophrenia 1 (DISC1) and its molecular cascade have an influence on the pathophysiology of schizophrenia and bipolar disorder." (PMID 31530853, 2019). "Apart from the involvement in the schizophrenia pathogenesis downstream of DISC1, Akt has been independently suggested as a schizophrenia susceptibility gene in the genetic linkage and association studies." (PMID 31819047, 2019). "We also report abnormalities in lactate levels in an animal model of schizophrenia, the GFAP DISC1 mouse, and frontal cortical neurons differentiated from iPSCs of a patient with the DISC1 mutation." (PMID 30911039, 2019). "Consistently, mutations in PCM1 were associated with schizophrenia 75, 76, 77, and PCM1, Hook3, DISC1, and SDCCAG8 were implicated in maintaining neural progenitor cells and neuronal migration during cortical development." (PMID 31023719, 2019). "The density of DISC1-expressing astrocytes is largely reduced in the dentate gyrus of hippocampus in schizophrenia patients compared with healthy controls." (PMID 30459650, 2018). "Intriguingly, the interactome analysis of both DISC1, dysbindin-1, and CRMP2, which is another susceptibility gene for schizophrenia, revealed common protein interactions with microtubules, actin cytoskeleton, and proteins involved in intracellular transport." (PMID 30061532, 2018). "They found that disruption of DISC1 signalling at P7 was most effective at impairing working memory and dendritic complexity in the dentate gyrus, both of which are related to human schizophrenia pathology." (PMID 30008190, 2018). "Insoluble oligomers of DISC1 have indeed been found in postmortem brain samples of patients with schizophrenia." (PMID 30050571, 2018). "With this background, we would like to address a few studies focusing on NRG-1 and the DISC-1 and dysbindin-1 genes in relation to schizophrenia." (PMID 30214393, 2018). "For example, disrupted in schizophrenia 1 (DISC1), neuregulin 1 (NRG1) and CACNA1C mutations and polymorphisms are known to be associated with schizophrenia, bipolar disorder and major depression." (PMID 29794033, 2018). "Although GluN2B-containing NMDAR hypofunction and DISC1 alteration are implemented in the neuropathology of schizophrenia, the mechanism of their possible interactions are not clear." (PMID 30233316, 2018). "Our research has focused on the molecular and histological changes in the brain of disrupted in schizophrenia 1-locus impairment (DISC1-LI) mice, which is known to be relevant to the neuropathology of schizophrenia." (PMID 30208945, 2018). "This is the case of the disrupted in schizophrenia 1 (DISC1) gene, a schizophrenia-related gene, originally discovered in a large Scottish family with a high incidence of psychiatric symptoms." (PMID 30061532, 2018). "Disrupted-in-schizophrenia 1 (DISC1) is a key protein involved in behavioral processes and various mental disorders, including schizophrenia and major depression." (PMID 29467617, 2018). "The Rac1 protein is activated by the N-methyl-d-aspartate receptor (NMDAR) and is important for disrupted in schizophrenia 1 (DISC1) function in the maintenance of spine morphology and function." (PMID 29695761, 2018). "This type of effect has been reported for other kinesin 1 cargoes such as disrupted in schizophrenia (DISC1), a centrosomal protein that requires kinesin 1 to translocate away from the pericentriolar region and into the axon in neurons." (PMID 29445114, 2018).
schizophrenia (continued). "In accordance with this, DISC1, ANK3 and ASPM, whose mutations are associated with schizophrenia, bipolar disorder and autism spectrum disorder, have been shown to regulate Wnt/β-catenin signaling activity during cortical neurogenesis." (PMID 28103279, 2017). "By conditioning genome-wide linkage data for schizophrenia on DISC1, a peak of linkage at chromosome 16p was observed, near to NDE1 (nuclear distribution element 1)." (PMID 29142105, 2017). "A balanced t [q42.1; q14.3] translocation that disrupts DISC1 co-segregates with schizophrenia, major depression, and bipolar disorder." (PMID 29029423, 2017). "CCDC141 (also known as CAMDI) encodes the coiled-coil domain containing 141 protein and interacts with DISC1 (disrupted in schizophrenia 1) and MYL2 (phosphorylatable myosin light chain)." (PMID 28379579, 2017). "For example, Disc1 is also located in mitochondria, which are involved in some human diseases of the central nervous system, including schizophrenia and bipolar disorder." (PMID 28125008, 2017). "Mutant models of DISC1 gene function display anatomical, behavioural, and pharmacological phenotypes relevant to several neuropsychiatric disorders, including schizophrenia and depression." (PMID 27725886, 2016). "The protein disrupted in schizophrenia-1 (DISC-1) was recently identified as a novel RBP and a component of RNP granules." (PMID 26904297, 2016). "Kalirin-7 also interacts with genetic factors for schizophrenia (e.g., DISC1, NRG1) in regulating dendritic morphology and spine plasticity." (PMID 28036092, 2016). "Candidate genetic factors for schizophrenia, including disrupted in schizophrenia 1 (DISC1), neuregulin-1 (NRG1), and dysbindin, have distinct roles in synapse-specific mechanisms and directly affect functional signaling involved in synaptic transmission." (PMID 28036092, 2016). "DISC1 was first discovered due to a balanced chromosomal translocation in a family with a high incidence of schizophrenia and other major mental illness." (PMID 26553875, 2016). "A meta-analysis found that putative schizophrenia risk variants in genes including ZNF804A, PRODH, DISC1 and PPP1R1B, reduced functional connectivity, while the genetic changes examined had no overall effect on structural connectivity." (PMID 27450778, 2016). "Gomafu is downregulated in the cortex of schizophrenia patients, and the knockdown of Gomafu in neurons can affect the splicing patterns of schizophrenia-related genes DISC1 and ERBB412." (PMID 27251103, 2016). "Similar results were obtained after PFC perturbations in rats and in DISC1 and neuregulin-1 mouse models of schizophrenia (for review see47, 64)." (PMID 26608841, 2015). "The disrupted-in schizophrenia 1 (DISC1) gene was discovered at the breakpoint of inherited balanced chromosomal translocation in a Scottish family suffering from major depression, schizophrenia, and bipolar disorder." (PMID 25805966, 2015). "The expression of the NX1 and NX3 genes was recently shown to be dysregulated in the Disc1 (disrupted in schizophrenia 1) mouse model of schizophrenia." (PMID 26078884, 2015). "These molecules regulate schizophrenia and depression-associated pathways downstream of DISC1 and further implicate neurodevelopment, synaptic processes such as spine regulation, and cAMP and NMDA signaling in schizophrenia and depression-associated behaviors." (PMID 25762938, 2015). "The objective of the study was to examine several polymorphisms in DISC1 and CTNX3 genes as possible risk factors in schizophrenia." (PMID 25889058, 2015). "Expression of the NX1 and NX3 genes in the brain appears to be regulated by a schizophrenia-related protein, DISC1." (PMID 26078884, 2015). "Neuron-specific overexpression of the truncated DISC1 also resulted in drastic phenotypes: enlarged lateral ventricle, reduced number of PV-positive interneurons and schizophrenia-like behavioral abnormalities." (PMID 25805966, 2015).
schizophrenia (continued). "A chromosomal translocation intersecting DISC1 was first found in a Scottish pedigree with a high frequency of severe psychiatric disorders, including schizophrenia, depression, and bipolar disorder." (PMID 25762938, 2015). "Our results indicate that the NX/NL synaptic complex is intrinsically involved in the regulation of DISC1 function, thus contributing to a better understanding of the pathology of schizophrenia." (PMID 26078884, 2015). "For example, poly I:C MIA exacerbated the schizophrenia-like phenotype in Disc1-L100P heterozygotes." (PMID 25762938, 2015). "Lastly, since a great deal interest surrounds the possible role of kynurenines in the initiation and development of schizophrenia, we examined the protein DISC1." (PMID 26365611, 2015). "Transgenic mice expressing mutant human DISC1 specifically in the forebrain also show behavioral deficits similar to schizophrenia." (PMID 26733803, 2015). "GABAergic interneuron dysfunction is believed to play a central role in the pathogenesis of schizophrenia and the interaction between DISC1 and GABA signalling has been shown to regulate neurogenesis in mice." (PMID 25708817, 2015). "The localization of Kalirin-7 and the duration of Rac1 activation are regulated by the schizophrenia-related factor DISC1 (disrupted-in-schizophrenia 1)." (PMID 25879033, 2015). "The susceptibility genes (such as DISC1, RELN, GABA, SHANK3, NRXN1, NTNG1, etc.), which were associated with schizophrenia, also confer risk to ASD." (PMID 26204268, 2015). "Consistently, increased ionic detergent-insoluble form of DISC1 protein and co-aggregation of DISC1 and dysbindin-1 are demonstrated in the postmortem brains of patients with affective disorders or schizophrenia as compared with control subjects." (PMID 27462430, 2015). "The 129S6/SvEv substrain is important as a potential mode for schizophrenia, because there is a spontaneous deletion in the DISC1 gene (disrupted in schizophrenia-1)." (PMID 27081652, 2015). "A decrease in adult neurogenesis was reported in mutant mice of schizophrenia-associated genes such as reeler mice, NPAS3-KO mice and DISC1 knockdown mice." (PMID 24528488, 2014). "Based on these results, the relevance of Disc1 L100P as a mouse model of schizophrenia should be re-evaluated." (PMID 25487992, 2014). "These included genes linked to bipolar disorders and schizophrenia, such as CACNA1C and DISC1, as well as the COMT gene." (PMID 24409157, 2014). "The second group involves DISC1 and ERBB4; the latter being the gene with the highest ranking in terms of strength of association with schizophrenia GWAS data sets among the oligodendroglial and myelin related genes." (PMID 25506321, 2014). "Remarkably, disrupted in schizophrenia-1 (DISC1), a protein involved in the pathophysiology of schizophrenia and other psychiatric disorders, directly binds SR, protecting it from ubiquitin-mediated degradation." (PMID 24795622, 2014). "As mentioned, the mental disorders reported in the Scottish family as a consequence of the DISC1 alteration include schizophrenia, BD and MD." (PMID 25126062, 2014). "For example, in a complex disorder such as schizophrenia, it has been consistently reported that several specific signaling molecules, including AKT, DISC1, NRG1 and calcineurin, are associated with the disease." (PMID 25290670, 2014). "GSK-3β has also been involved in the disrupted in schizophrenia 1 (DISC1)-mediated regulation of adult neurogenesis." (PMID 23805076, 2013). "It is not uncommon to find the same susceptibility gene for different psychiatric disorders, as exemplified by the DISC1 translocation in a Scottish schizophrenia family." (PMID 23823008, 2013). "The Disc1 mouse models are popular genetic models for studying gene-environment interactions in schizophrenia." (PMID 24027503, 2013).
schizophrenia (continued). "More recently, it has been reported that knockdown of Disc1 (disrupted in schizophrenia 1), specifically in adult-born DG neurons, results in enhanced excitability." (PMID 23840971, 2013). "The Disc1 gene was originally discovered in a Scottish family with a high incidence of psychiatric disorders, including schizophrenia and bipolar disorder." (PMID 23840971, 2013). "Utilization of DISC1 genetically engineered mice served as a model for mental illnesses such as schizophrenia, and analysis of these mice showed that dominant-negative DISC1 mice display behavioral abnormalities and a depression-like deficit." (PMID 23618463, 2013). "FEZ1 was recently shown to interact with DISC1, a known candidate gene for both autism and schizophrenia." (PMID 24063311, 2013). "For example, DISC1, another NDEL1-interacting partner, plays essential roles in neuronal proliferation, neuronal migration and axon guidance and has been implicated in schizophrenia and related psychiatric disorders." (PMID 23861741, 2013). "DISC1 inactivates GSK3-beta signaling, another key regulator of adult neurogenesis implicated in both schizophrenia and bipolar disorder." (PMID 23882188, 2013). "Ultra-rare missense mutations in patients with schizophrenia have been reported for APP PCM1, and indeed DISC1." (PMID 21195721, 2012). "ITSN1 has been implicated in neurodegeneration and the identification of ITSN1 as a binding partner for DISC1 (disrupted in schizophrenia 1) suggests a potential role for ITSN1 in psychiatric disease as well." (PMID 22558309, 2012). "We present the characterization of several of these new targets which implicate ITSNs in the regulation of the Rab and Arf GTPase pathways as well as regulation of the disrupted in schizophrenia 1 (DISC1) interactome." (PMID 22558309, 2012). "Genetic association studies in cohorts of schizophrenia patients further revealed an epistatic interaction between FEZ1 and DISC1 for risk of schizophrenia." (PMID 22891052, 2012). "Mutant Disc1 mice present enlarged lateral ventricles in juveniles, and behavioral aspects similar to the pathology of patients with schizophrenia." (PMID 22891052, 2012). "The critical issue is what we can learn from the identification of DISC1 regarding the specifics and generalities of the biological underpinning of schizophrenia and other major mental illness." (PMID 21195721, 2012). "PACAP markedly decreases the interaction between DISC1 and the DISC1-binding zinc-finger protein (DBZ), which is suggested to be one of molecular pathways that underlies the pathogenesis of schizophrenia." (PMID 23060763, 2012). "For example, the interaction of the disrupted in schizophrenia 1 (DISC1) with PDE4B1 or PDE4B3 and mutations in DISC1 associates with schizophrenia." (PMID 22830422, 2012). "The observed increase in mutation burden in patients provides further support for the role of the DISC1 pathway in schizophrenia." (PMID 21853134, 2011). "Many association studies have replicated a positive association of rs821616 which is a missense polymorphism leading to a serine-to-cysteine substitution at amino acid 704 (Ser704Cys)in DISC1 with schizophrenia." (PMID 21569632, 2011). "Disrupted in Schizophrenia, DISC1, is one of the most convincing candidate genes for schizophrenia and related major mental illness." (PMID 21298101, 2011). "In recent years, DISC1 has emerged as one of the most credible and best supported candidate genes for schizophrenia and related neuropsychiatric disorders." (PMID 21853134, 2011). "To explore the role of genetic variation in DISC1 and 10 of its interaction partners in the etiology of schizophrenia, we sequenced the coding exons and splice junctions of the genes using massively parallel 454 sequencing in pooled samples." (PMID 21853134, 2011).
schizophrenia (continued). "DISC1 is present in regions (i.e. cerebral cortex and hippocampus) of the brain that shows abnormality in schizophrenia patients; aberrant DISC1 expression results in reduced volume of frontal cortical gray matter." (PMID 19128481, 2009). "DISC1 is a gene that is disrupted in patients with schizophrenia and other severe neuropsychiatric disorders in one Scottish family." (PMID 19197363, 2009). "Genetic and biological evidence supports a role for DISC1 across a spectrum of major mental illnesses, including schizophrenia and bipolar disorder." (PMID 19300510, 2009). "Disrupted in schizophrenia 1 (DISC1) is a protein with a wide array of functions suspected to be involved in the pathogenesis of schizophrenia." (PMID 19445674, 2009). "Several genes, e.g., DISC1 and NRG1, which have been repeatedly shown to be associated with susceptibility to schizophrenia, are involved in GSK-3/Wnt regulatory pathways." (PMID 18702828, 2008). "The results also highlight the success of our precision psychiatry approach: the biological definition of a subset of schizophrenia by identifying DISC1 protein aggregates, the generation of a corresponding animal model and a successful pharmacotherapy of a clinically relevant phenotype." (PMID 41639125, 2026). "It has been suggested that the full-length DISC1 protein, when post-translationally modified, can contribute to the development of some sporadic forms of schizophrenia because of aberrant multimerization, which converts the protein into an insoluble form prone to aggregation." (PMID 39940735, 2025). "For example, proteolysis of DISC1 during development of the nervous system can contribute to its insufficiency and result in the aberrant formation of neural circuitry, which is a contributory factor to the development of schizophrenia." (PMID 39940735, 2025). "Interestingly, one of the genes with a high number of Cn SNPs in C58/J mice, Disc1 (Disrupted-in-schizophrenia 1), has a strong participation in proliferation, morphogenesis, differentiation, and migration during hippocampal adult neurogenesis." (PMID 38409172, 2024). "Moreover, DISC1 and BBS4 have been shown to be required to PCM1 localization as well and are synergistically associated with mental pathologies, such as schizophrenia." (PMID 38961488, 2024). "Although no common variants at the DISC1 locus associated with schizophrenia have been found in broader populations, this does not exclude the possibility that DISC1 indicates central biological pathways for mental health issues." (PMID 38920990, 2024). "In this regard, DISC1 may impact developmental pathways and pathophysiological mechanisms related to schizophrenia, among which modifications in the Hh signalling pathway appear to be an exciting candidate deserving further investigation." (PMID 38920990, 2024). "Gathering together the long-recognized alterations in dopaminergic neurotransmission in schizophrenia, a surprising impact of DISC1 on dopaminergic function has been elucidated with increasing attention to its role in the dopamine D2 receptor (D2R) regulation and the response to antipsychotics." (PMID 36831241, 2023). "The disrupted‐in‐schizophrenia 1 (DISC1) gene was initially identified in a Scottish family with an unusually high prevalence of mental disorders, including schizophrenia, and the disruption was due to a balanced translocation of the chromosome (1:11) (q43, q21)." (PMID 37016810, 2023). "When disrupted-in-schizophrenia-1-Δ3 (DISC1-Δ3), a major DISC1 variant lacking exon 3, was overexpressed in OPCs, the mutant mice exhibited schizophrenia-like behavior." (PMID 37401986, 2023). "Moving forward with the relevance of DISC1 to schizophrenia modeling, previous studies have shown that both DISC1 and NudE Neurodevelopment Protein 1 (NDEL1) can regulate the cell cycle by interacting with glycogen synthase kinase 3 beta and LIS1-dynein, respectively." (PMID 35948659, 2023).